REN (renin)
Diseases named in the same sentence as REN in open-access papers (continued):
Sharing a sentence is not in itself a finding about the gene and the disease.
cancer (continued). "Renin secretion is important in cancer development as it regulates the production of angiotensin II, which has been shown to stimulate cancer cell growth and proliferation." (PMID 36743211, 2023). "The involvement of the renin-angiotensin pathway in both the regulation of the cardiovascular system and in oncogenesis raises the question of the prognostic impact of RABs in cancer patients experiencing life-threatening complications." (PMID 37370793, 2023). "Given the patient’s previous cancer history, elevated aldosterone/renin ratio, and mass size, our multidisciplinary tumor board decided to proceed with a left adrenalectomy." (PMID 38026486, 2023). "Of note is AGT, encoding for the angiotensinogen, a component of the renin-angiotensin system (RAS), responsible for the final activation of angiotensin-converting enzymes (ACEs) and that has been shown to be involved in cancer biology and progression." (PMID 37041632, 2023). "We previously reported the relevance of VEGF-A and some components of the renin–angiotensin-aldosterone system (RAAS) in the response to anti-angiogenic therapy in cancer patients." (PMID 35804826, 2022). "The ACE2 receptor is also involved in the renin–angiotensin system (RAS) which plays an important role in regulating blood pressure as well as cancer progression." (PMID 36293371, 2022). "Previous research indicates that the renin-angiotensin system has a role in multiple cancer types, likely due to its regulation of angiogenesis." (PMID 35659616, 2022). "These pathways include JAK/STAT Signaling, Renin-Angiotensin Signaling, Molecular Mechanisms of Cancer, IL-8 Signaling, CXCR4 Signaling, LPS-Stimulated MAPK Signaling, EGF Signaling, PEDF Signaling, NF-κB Activation by Viruses, and B Cell Receptor Signaling." (PMID 34983392, 2022). "Since tumor size is part of the staging system, with larger tumors classified as later stages, it is possible that the up-regulation of REN, which induces angiogenesis, is a factor in the progression of cancer to a later stage." (PMID 35659616, 2022). "KEGG pathway analysis showed that the enrichment terms converged on the PI3K-Akt signaling pathway, microRNAs in cancer, transcriptional misregulation in cancer, renin secretion, and hematopoietic cell lineage, among others." (PMID 36578040, 2022). "This study provides not only a new strategy for cancer therapy by targeting the renin‐angiotensin system, but also a new avenue to modulate GPCR signaling by RNA activation." (PMID 35712764, 2022). "The role of the renin-angiotensin system (RAS) in cancer growth and progression is well recognized in humans." (PMID 36006326, 2022). "ESC-like cells in VAs, cancer, and fibroproliferative conditions express components of the renin-angiotensin system (RAS) – a homeostatic endocrine signaling cascade that regulates cells with ESC characteristics." (PMID 35574555, 2022). "The renin-angiotensin pathway plays a crucial role in cancer biology and affects tumor growth by remodeling the tumor microenvironment." (PMID 34590603, 2021). "The presence of individual elements of the renin-angiotensin (RA) system allows to control many processes, ranging from the memorization to pro-cancer processes." (PMID 33673178, 2021). "The presence of a renin expressing cell in ccRCC stroma has previously been reported, and subsequent work has identified it as a cancer stem cell." (PMID 34884982, 2021). "In conclusion, these results support the clinical utility of RAS gene SNPs AT2R rs11091046, REN rs12750834, and ANG rs699 in the genetic cancer risk assessment of patients and families with BC." (PMID 34898568, 2021). "The renin-angiotensin system plays an important role in cancer progression in different malignancies." (PMID 33883980, 2021). "In summary, this candidate gene association study supports the clinical utility of the RAS gene SNPs AT2R rs11091046, REN rs12750834, and ANG rs699 in the genetic cancer risk assessment of patients and families with BC." (PMID 34898568, 2021).
cancer (continued). "Of the 65 pathways identified for ICH and the 25 for SAH-V (current study), five overlapped including alpha adrenergic signaling, renin–angiotensin signaling, phospholipase C, corticotropin-releasing hormone signaling, and cancer mechanisms." (PMID 31595394, 2020). "Components of the renin-angiotensin system (RAS) are expressed by cancer stem cells (CSCs) in many cancer types." (PMID 33147716, 2020). "Dysregulation of the renin-angiotensin system is involved in cancer cell migration and invasion, as well as metastasis in malignant tumors, including CRC." (PMID 24959250, 2014). "AT-II also induces the expression of iNOS, an inflammatory marker, along with 8-OHdG in cancer cells through the activation of AT-1R, suggesting a cross-link between renin-angiotensin system-related inflammation and oxidative stress in cancer tissue." (PMID 24959250, 2014). "Targets specific to BMAL1 were enriched in a wide variety of processes associated with protein assembly, nucleic acid metabolism as well as renin-angiotensin, hormone and cancer signaling." (PMID 21731503, 2011). "In grade III intraductal carcinoma, the cancer cells show little (pro)renin staining, and instead, the fibroblasts frequently show the greatest abundance of the antigen." (PMID 16755291, 2006). "The fact that multifunctional hormonal systems, such as the renin–angiotensin–aldosterone system, influence tumour growth and angiogenesis provides interesting pathways to the study of cancer." (PMID 15785746, 2005). "The pathway enrichment analysis showed that T2c was enriched with the pathways, such as the leukocyte transendothelial migration, adherens junction, and NF‐κB signaling pathway, while T3b was enriched with the renin–angiotensin system, hippo signaling, and cancer pathways as we reported." (PMID 41386760, 2025). "The paracrine renin–angiotensin system is implicated in cellular proliferation, inflammation, invasion and adhesion, angiogenesis, endothelial-to-mesenchymal transition (EMT), and cancer metastasis." (PMID 39941158, 2025). "There is increasing evidence of the role of the renin–angiotensin system in cancer metastasis." (PMID 39941158, 2025). "Excessive secretion of renin, angiotensin, and angiotensin I by carcinoma cells may lead to paraneoplastic hypertension." (PMID 40594910, 2025). "Finally, REN exhibited protective trends in cancers such as KIRC and kidney renal papillary cell carcinoma (KIRP), while being associated with increased risk in LGG and UCS, highlighting its potential as a prognostic marker." (PMID 39635438, 2024). "Specifically, as a key active peptide of the renin-angiotensin system, binding of angiotensin II to the angiotensin II type one (AT1) receptor promotes cell proliferation, angiogenesis, and inflammation, increasing the risk of cancer." (PMID 38487860, 2024). "Intriguingly, REN copy number alterations across all cancers were associated with lower PFS and OS when corrected for age, sex, and tumour type, suggesting REN may play a wider role in cancer progression." (PMID 38607073, 2024). "Since ACEs and ARBs share a main mechanism of action, which is to act as renin–angiotensin–aldosterone system (RAAS) antagonists, they inhibit angiogenesis and reduce the induction of cancer growth, which may decrease cancer risk over time." (PMID 36831338, 2023). "However, previous animal studies seem to suggest the important roles of the renin-angiotensin system on cancer growth and metastasis." (PMID 37175975, 2023). "Preclinical studies indicate that the concurrent use of inhibitors of the renin–angiotensin–aldosterone system (RAAS) may improve outcomes in broad groups of patients with cancer." (PMID 35065368, 2022). "HF drugs such as beta-blockers or inhibitors of the renin–angiotensin–aldosterone system might exert a protective effect on the heart even before the start of cancer therapies." (PMID 34318387, 2022).
cancer (continued). "Components of the RAS, i.e., renin, pro-renin receptor (PRR), angiotensin-converting enzyme (ACE), ACE2, angiotensin II receptor 1 (AT1R), and angiotensin II receptor 2 (AT2R), have been associated with the development of cancer." (PMID 33916968, 2021). "The KEGG pathways associated with up-regulated circRNAs in B SPZ were linked to long-term depression and potentiation, central carbon metabolism in cancer, phosphatidylinositol signaling system, renin secretion, Rap1 signaling, cell cycle, Hedgehog signaling, and the circadian rhythm." (PMID 32754116, 2020). "Renin-angiotensin system mainly controls blood pressure; however, cancer cells and their microenvironment also express renin and angiotensin, which play a pathophysiological role in cancer development." (PMID 30498512, 2018). "Furthermore, abnormalities in the renin-angiotensin system closely correlate with the enhancement of cancer cell migration, invasion and metastasis, which are correlated with poor prognosis." (PMID 24959250, 2014). "Increase in activity of renin-angiotensin system has been reported in cancer conditions." (PMID 24381940, 2013). "In cancer, although, (pro)renin mRNA and protein are both found in fibroblasts." (PMID 16755291, 2006). "However, confirming the previously reported in situ hybridisation data, there was significantly less (pro)renin mRNA in carcinoma than in normal tissue." (PMID 16755291, 2006). "The involvement of the renin-angiotensin pathway in both the regulation of the cardiovascular system and in tumorigenesis raises the question of the prognostic impact of renin-angiotensin system blockers (RABs) in cancer patients experiencing life-threatening complications." (PMID 37370793, 2023). "Neurohumoral response includes the renin-angiotensin-aldosterone system (RAAS), which can be chronically stimulated, representing a hallmark of HF, and it has also been established that RAAS is frequently altered in a variety of cancer types, which is associated with a poor prognosis." (PMID 34281199, 2021). "In addition, the potential roles of the SARS-CoV-2 receptor ACE2 and the renin-angiotensin system (RAS) in cancer patients with SARS-CoV-2 infection remain unclear." (PMID 34671200, 2021). "Increased activation of bio-hormonal systems such as sympathetic nervous and renin-angiotensin-aldosterone systems, which is detected in cancer microenvironment, could be also responsible for LA remodeling in the these patients, as it was previously showed in patients with other pathologies." (PMID 30934794, 2019). "The cancer-derived PGE2 might also stimulate renin secretion." (PMID 28498361, 2017). "Renin–angiotensin system inhibitors ACEIs/ARBs might influence tumor angiogenesis by reducing vascular endothelial growth factor expression and induce apoptosis in cancer cells." (PMID 27965461, 2017). "An emerging body of literature links the role of the renin–angiotensin system (RAS), well-known for its function in the cardiovascular system, to the progression of cancers." (PMID 38607073, 2024). "The renin-angiotensin-aldosterone system (RAAS), is an old system with new fundamental roles in cancer biology which influences cell growth, migration, death, and metastasis." (PMID 37891636, 2023). "In hypertensive individuals, an overactive renin-angiotensin system (RAS) increases the incidence and mortality of cancer." (PMID 38053135, 2023). "We highlight the critical role of the renin–angiotensin system (RAS) on GB cancer stem cells and the tumor microenvironment which, in turn, influences cancer stem cells in driving tumorigenesis and treatment resistance." (PMID 34439159, 2021). "The local renin–angiotensin system (RAS) plays an important role in the pathophysiology of the prostate, including cancer development and progression." (PMID 32872192, 2020). "Angiotensin II (Ang II), the biologically active peptide of the renin-angiotensin system (RAS), plays a critical role in the metastasis of various cancers." (PMID 31133857, 2019).
cancer (continued). "The renin–angiotensin receptor AT2R controls systemic blood pressure and is also suggested to modulate metastasis of cancer cells." (PMID 31484460, 2019). "We have previously demonstrated the putative presence of two cancer stem cell (CSC) subpopulations within moderately differentiated oral tongue squamous cell carcinoma (MDOTSCC), which express components of the renin–angiotensin system (RAS)." (PMID 28775982, 2017). "Renin-angiotensin system inhibitors (RAAS inhibitors) are frequently recommended as first-line agents due to their favorable cardiovascular profile and potential synergistic effects with some cancer therapies." (PMID 42131090, 2026). "In addition to proteins known to directly bind REN, such as Cul3, RBX1, and KCTD15, we recovered various potential REN interactors including SALL4, a cell stemness regulator aberrantly activated in several types of human cancers." (PMID 38062245, 2024). "Along with the prominent function of the renin-angiotensin-aldosterone system as the most important blood pressure regulator, RAAS could be related to different pathological conditions such as cancer and oncogenesis." (PMID 37891636, 2023). "Thus, mounting evidence supports the use of medications such as aspirin, statins, inhibitors of the renin-angiotensin-aldosterone system (RAAS), thiazolidinediones, and metformin for the prevention of both CVD and cancer." (PMID 37520844, 2023). "There is accumulating evidence for the critical role of cells that possess embryonic stem cell (ESC) characteristics and the expression of components of the renin-angiotensin system (RAS), in different types of vascular anomalies (VAs), cancer, and fibroproliferative conditions." (PMID 35574555, 2022). "The renin-angiotensin system is a key regulator of blood pressure homeostasis, with its primary effector, the angiotensin II type 1 receptor (AT1R), mediating vasoconstriction and processes fundamental to cancer progression, including proliferation, angiogenesis, and metastasis." (PMID 41408463, 2026). "Since some cancers express renin, ACE, and Ang II receptors, there is the potential involvement of the local renin-angiotensin system in growth-promoting events, therefore raising the prospect that Ang II may be involved in the development of cancer, as suggested by Sun." (PMID 37627246, 2023). "The renin-angiotensin system (RAS) maintains blood pressure and fluid volume by controlling sodium absorption, vascular tone and hormone release, and its involvement in cancer is an emerging field of research, particularly its paracrine role in regulating CSCs." (PMID 34428252, 2021). "The mechanism of cancer cachexia is not known, but Indeed, cancer patients, with and without cachexia exhibit the high levels of serum brain natriuretic peptide (BNP), renin and aldosterone." (PMID 35911555, 2022). "Extracellular vesicles from osteoclasts dose-dependently stimulated (pro)renin activity, while extracellular vesicles from 4T1 cancer cells, in which we did not detect PRR, did not activate (pro)renin." (PMID 33911158, 2021).
tumor (150 papers, 1979 to 2026). "Metabolic pathways such as cGMP-PKG signaling pathways, renin-angiotensin system was implicated in the regulation of the complex tumor microenvironment." (PMID 41579221, 2026). "A high aldosterone level with a suppressed level of renin point to the adrenal cause (tumor, hyperplasia), where abnormal autonomous hypersecretion of aldosterone suppresses the secretion of renin by the kidneys." (PMID 25177679, 2014). "Aberrant Hh, Hippo, and Renin-angiotensin signaling could lead to a series of diseases associated with abnormal lipid metabolism, while it can also advance tumor progression and metastases." (PMID 36949462, 2023). "We hypothesized that renin secretion by the tumor was the cause of hypertension." (PMID 39650950, 2024). "AGT, encoded by Agt gene, is a 452-amino-acid-residue protein that can be cleaved by renin to generate angiotensin I (AngI) which has been demonstrated to exert antiangiogenic properties in vitro and in vivo, suggesting the underlying anti-tumor activity of AGT." (PMID 29121993, 2017). "The renin-angiotensin system (RAS) seems to be involved in tumor growth, by inducing angiogenesis and tumor proliferation as well as in the pathogenesis of fibrosis, mainly due to its ability to activate TGFβ signaling, a key feature of fibrosis." (PMID 40214893, 2025). "The imbalance of the renin–angiotensin system (RAS), characterized by the overactivation of the pro-tumor ACE/AngII/AT1R axis, is closely linked to tumor growth, angiogenesis, metastasis, and poor prognosis." (PMID 41301459, 2025). "For our patient, tumor resection was successful in reducing her renin back to normal values within 3 weeks." (PMID 40546339, 2025). "This real-world correlation hints that targeting the renin–angiotensin system can positively influence tumor progression." (PMID 40644464, 2025). "Research continues to reveal the complexity of the renin–angiotensin system and its role in physiological and pathological processes, particularly in tumor biology through its paracrine function." (PMID 39941158, 2025). "Elevated plasma renin activity has been observed in the renal veins draining tumor-bearing kidneys, along with an increased renin content within the tumor tissue itself." (PMID 41301732, 2025). "While removing the offending renin-producing tumor as the cure, it is often vital to emergently employ BP medications to reduce symptoms and ensure they are stabilized for their upcoming surgical resection." (PMID 40546339, 2025). "The renin–angiotensin system (RAS) is increasingly being recognized to play a role in the tumor microenvironment, promoting tumor growth." (PMID 38922022, 2024). "Based on the clinical findings and biochemical abnormalities, we were expecting this tumor to be aldosterone-secreting, but both serum aldosterone and renin levels were normal in our patient." (PMID 38827415, 2024). "The first reported pregnancy complicated by a renin-producing tumor resulted in intrauterine fetal demise (IUFD) at 19 weeks of gestation, despite tumor resection at 16 weeks of gestation." (PMID 39650950, 2024). "Angiotensin II regulates blood pressure through gut microbiota metabolites, thereby involving intestinal flora participation in the renin-angiotensin-system and the formation of the suppressive tumor microenvironment." (PMID 37680706, 2023). "Page kidney can also result when there is external compression of the kidneys due to a tumor, lymphocele, or urinoma, and subsequent renin–angiotensin–aldosterone system activation." (PMID 36845773, 2023). "Comparing normalised expression values, we found a significant increase in renin expression in tumours compared to normal human mesangial-like cells (Wilcoxon rank-sum test, p < 0.05)." (PMID 37749094, 2023). "Plasma aldosterone and renin levels, tumor size, and estimated glomerular filtration rate (eGFR) were positive predictive factors in the surgery-track group, whereas negative CT findings were negative predictive factors." (PMID 38081870, 2023).